SIRT1 (sirtuin 1)
Diseases named in the same sentence as SIRT1 in open-access papers (continued):
Sharing a sentence is not in itself a finding about the gene and the disease.
neuroblastoma (continued). "Our data demonstrate the important roles of SIRT1 in N-Myc oncogenesis and SIRT1 inhibitors in the prevention and therapy of N-Myc–induced neuroblastoma." (PMID 21698133, 2011). "In HT-22 neuroblastoma cells however, SIRT1 is in the nucleus even following HCA-induced oxidative stress." (PMID 19116652, 2008). "With the aim of investigating whether 24-OHC might modulate the expression of PGC1α, a well-known downstream target of SIRT1, SK-N-BE neuroblastoma cells were incubated up to 6 h with the oxysterol at the physio-pathological concentration of 1 μM." (PMID 36978879, 2023). "The results could reveal, for the first time, a beneficial role of 24-OHC in reducing tau accumulation in the SK-N-BE neuroblastoma cells by acting on the SIRT1/PGC1α/Nrf2 signaling pathway leading to ubiquitination and degradation of tau through UPS." (PMID 36978879, 2023). "In this regard, a beneficial effect of 24-OHC was demonstrated in SK-N-BE neuroblastoma cells by our group, due to its ability to up-regulate both expression and synthesis of SIRT1, and consequently to lead to tau deacetylation and to prevent its phosphorylation." (PMID 36978879, 2023). "miR-181 significantly inactivated the sirtuin 1 (SIRT1)/peroxisome proliferator-activated receptor γ coactivator-1α (PGC-1α)/nuclear factor erythroid 2-related factor 2 (Nrf2) signaling cascade in CPF-treated neuroblastoma cells." (PMID 36387211, 2022). "Therefore, miR-181 promoted CPF-induced neuroblastoma cell pyroptosis through downregulation of the SIRT1/PGC-1α/Nrf2 signaling pathway." (PMID 36387211, 2022). "Moreover, we have confirmed that osmotin action is mainly attributed to the activation of AdipoR1, as the silencing of AdipoR1 expression abolished the osmotin ability to activate p-AMPK and SIRT1 in SH-SY5Y neuroblastoma cells." (PMID 35204143, 2022). "Also, it was reported that SIRT1 stabilizes N-Myc protein and promote neuroblastoma cell proliferation." (PMID 34650436, 2021). "In MC65 human neuroblastoma cells, 100 μM phytic acid in the presence of tetracycline resulted in reduced concentrations of hydrogen peroxide and increased concentrations of proteins responsible for autophagy and housekeeping of the neuroblastoma cells (beclin-1 and SIRT1)." (PMID 34356337, 2021). "Therefore, identifying the functional correlation between SIRT1 and GSK3β is important for the development of novel therapies for neuroblastoma." (PMID 32158616, 2020). "Differentiated neuroblastoma cells were cultured with 75 mM glucose for 96 h to explore whether high glucose could induce downregulation of SIRT1." (PMID 29892266, 2018). "Additionally, neuroblastoma cells treated with resveratrol also underwent apoptosis and showed a downregulaton of SIRT1." (PMID 24603648, 2014). "This study evaluated whether activation of Sirt1 by the anti-cancer agent, β-lapachone (β-lap), induces autophagy in human neuroblastoma SH-SY5Y cells, thereby reducing intracellular levels of polyQ aggregates and their concomitant cytotoxicity." (PMID 23762270, 2013). "Importantly, N-Myc siRNA-1 and N-Myc siRNA-2 significantly reduced SIRT1 mRNA and protein expression in the two neuroblastoma cell lines." (PMID 21698133, 2011). "Our data suggest that repression of SIRT1 with specific inhibitors, such as Cambinol and Tenovin-6, could be an effective strategy for the prevention and therapy of N-Myc-induced neuroblastoma, and possibly other Myc-induced cancers." (PMID 21698133, 2011). "In this study, we have shown that N-Myc oncoprotein up-regulates SIRT1 gene transcription by directly binding to its gene promoter in neuroblastoma cells, that forced over-expression of N-Myc in normal cells induces SIRT1 gene expression, and that SIRT1 induces neuroblastoma cell proliferation." (PMID 21698133, 2011).
neuroblastoma (continued). "The evidence from the preclinical studies showed that the cognitive enhancing activity of EBN on hippocampal neurons (human SH-SY5Y neuroblastoma cells) could be due to increasing the SIRT1 expression in the pyramidal layer and dentate gyrus of the hippocampus." (PMID 33806762, 2021). "Finally, we examined whether suppression of SIRT1 activity impaired the progression of established neuroblastoma in vivo." (PMID 21698133, 2011). "Our results suggest that SIRT1 and AROS suppress GSK3β activity and acetylation, regulating the chemoresistance of doxorubicin in neuroblastoma." (PMID 32158616, 2020). "Based on recent reports on the role of SIRT1 in brain tumors, we first explored the effects of SIRT1 on apoptosis induced by DOX in human neuroblastoma SH-SY5Y cells." (PMID 32158616, 2020). "Here, we demonstrated that depletion of SIRT1 and AROS increases doxorubicin-mediated apoptosis in human neuroblastoma SH-SY5Y cells." (PMID 32158616, 2020). "Taken together, our results suggest that SIRT1 and AROS inhibit GSK3β activity and provide additional insight into drug resistance in the treatment of neuroblastoma." (PMID 32158616, 2020). "In neuroblastoma N2a cells expressing human APP Swedish mutant, overexpression of the SIRT1 gene increased ADAM10 protein expression." (PMID 27532339, 2016). "Pucci and colleagues showed very recently that Sirt1 silencing attenuates, while Sirt1 over-expression enhances, death of NG108-15 neuroblastoma cells induced by staurosporine and a host of other apoptotic agents." (PMID 24167473, 2013). "In this study, we have found that suppression of SIRT1 with Cambinol or Tenovin-6 re-activates MKP3 gene expression, reduces N-Myc protein level and induces neuroblastoma cell growth arrest." (PMID 21698133, 2011). "The present study aimed at supporting this concept by exploring, in SK-N-BE neuroblastoma cells, whether 24-OHC affected the neuroprotective SIRT1/PGC1α/Nrf2 axis." (PMID 36978879, 2023). "Furthermore, enhanced stability of SIRT1 by overexpression of Ceramide Kinase-Like Protein (CERKL) promoted the production of PINK1 and Parkin in human neuroblastoma cells of OGD/R." (PMID 36507335, 2022). "A recent study used SIRT1 and AROS to improve drug resistance in the treatment of neuroblastoma." (PMID 35967388, 2022). "Measuring the endogenous expression of neprilysin and insulin-degrading enzyme (IDE)—proteases involved in Aβ degradation—in human neuroblastoma SH-SY5Y cells, the expression of neprilysin was reduced by CM from HBMVECs with H/R treatment or with Sirt1 siRNA transfection." (PMID 33318474, 2020). "In summary, this study demonstrates that a novel pathway, involving transcriptional up-regulation of SIRT1, repression of MKP3 and consequent ERK protein phosphorylation, contributes to N-Myc oncoprotein stability, neuroblastoma cell proliferation and in vivo tumorigenesis." (PMID 21698133, 2011). "It is worth noting that repression of SIRT1 does not lead to cell death in the neuroblastoma cell lines tested." (PMID 21698133, 2011). "We next examined whether the effects observed with SIRT1, SIRT2, SIRT3, SIRT5, and SIRT6 on the regulation of LK-induced neuronal death extended to mouse HT-22 cells, a hippocampally-derived neuroblastoma cell line." (PMID 19116652, 2008). "In the present study we aimed at investigating, in SK-N-BE neuroblastoma cells, whether 24-OHC might modulate the SIRT1/PGC1α/Nrf2 signaling pathway by promoting tau ubiquitination and subsequently its proteolytic degradation by UPS, thus preventing intraneuronal tau accumulation." (PMID 36978879, 2023).
neuroblastoma (continued). "Given the critical role of SIRT1 in the NAD+ pathway and its importance in the control of cell differentiation, apoptosis, autophagy, metabolism, and stress response, STAU1 may indirectly regulate fate of neuroblastoma cells through controlling SIRT1 levels." (PMID 34633481, 2021).
pulmonary fibrosis (45 papers, 2020 to 2025). Chronic progressive interstitial lung disorder characterized by the replacement of the lung tissue by connective tissue, leading to progressive dyspnea, respiratory failure, or right heart failure. "There are reports in the literature that show SIRT1 is implicated in bleomycin-induced lung fibrosis." (PMID 36457607, 2022). "Additionally, we aimed to examine the possible association of SIRT1 with a known mediator of lung fibrosis, TGFβ1." (PMID 36457607, 2022). "A loss of Sirt1 may participate in the pathogenesis of pulmonary fibrosis (PF)." (PMID 35906886, 2022). "Only a few small molecules targeting SIRT1 have been studied for the treatment of pulmonary fibrosis." (PMID 38238857, 2024). "In summary, our results suggest that in mice with pulmonary fibrosis, the SIRT1/Nrf2 signaling pathway mediates the anti-fibrotic effects of liquiritigenin." (PMID 38238857, 2024). "To validate the role of the SIRT1/Nrf2 signaling pathway in mediating the effects of liquiritigenin in bleomycin-induced pulmonary fibrosis, we administered specific inhibitors of SIRT1 (EX527) or Nrf2 (ML385) 3 h before liquiritigenin treatment." (PMID 38238857, 2024). "In summary, our study results indicate that in mice with pulmonary fibrosis, the SIRT1/Nrf2 signaling pathway mediates the antioxidant stress effect of liquiritigenin." (PMID 38238857, 2024). "Our findings indicated liquiritigenin’s anti-pulmonary fibrosis effect, further, its effect was mediated by the SIRT1/Nrf2 signaling pathway." (PMID 38238857, 2024). "This seems contradictory to some extent, and further studies are necessary to clarify this, considering that SIRT1 expression in pulmonary fibrosis remains controversial." (PMID 37483618, 2023). "In bleomycin-induced EMT-related pulmonary fibrosis, SIRT1 expression is decreased, and the expression of type I collagen and α-SMA is increased." (PMID 37089962, 2023). "Overall, our results suggest opposing roles for Cdh1 and AROS in SIRT1 degradation during the development of pulmonary fibrosis and support pinosylvin as a therapeutic agent for human pulmonary fibrosis." (PMID 37258580, 2023). "After RSV treatment, SIRT1 expression is increased, which reduces alveolar epithelial cell damage, fibroblast proliferation, collagen deposition and pulmonary fibrosis, and is related to lung protection." (PMID 37089962, 2023). "To evaluate the role of SIRT1 in AT2-lineage cells during lung fibrosis, we intratracheally administered BLM to these mice." (PMID 37653024, 2023). "It has been reported that cigarette smoke-inactivated SIRT1 promotes autophagy-dependent senescence of AT2 cells to induce pulmonary fibrosis." (PMID 36275675, 2022). "Previous reports demonstrated that SIRT1 was downregulated in bleomycin (BLM)-induced pulmonary fibrosis, and treatment with an SIRT1 activator attenuated the EMT in BLM-induced fibrosis." (PMID 36499047, 2022). "Pulmonary Sirt1 and serum vitamin D (VD) decrease with physiological aging, activating TGF‐β1/IL‐11/MEK/ERK (TIME) signaling and promoting senescence‐associated pulmonary fibrosis (SAPF)." (PMID 35906886, 2022). "We found that pulmonary Sirt1 and serum vitamin D decreased with physiological aging, activating TGF‐β1/IL‐11/MEK/ERK signaling, and promoting senescence‐associated pulmonary fibrosis." (PMID 35906886, 2022). "Glrx inhibits Fas signaling, protects lung epithelial cells from apoptosis, and attenuates experimental lung fibrosis, and can mediate anti-apoptotic effects by activating NFκB or SirT1 via the reversal of S-glutathionylation." (PMID 35624731, 2022). "During the last decade, the role of sirtuins, and especially SIRT1, in lung fibrosis has been examined." (PMID 36457607, 2022). "To understand the importance of C/EBPβ acetylation in α-SMA gene expression and lung fibrosis, we used SIRT1, a class III histone deacetylase, to construct a cellular model of C/EBPβ deacetylation in vitro." (PMID 33663392, 2021).
pulmonary fibrosis (continued). "Overexpression of SIRT1 is found in synovial RA tissue and in LN, but SIRT1 has been shown to be reduced in peripheral blood mononuclear cells of SSc patients with pulmonary fibrosis and in lung tissues of bleomycin-induced lung fibrosis mice." (PMID 33920997, 2021). "For instance, Sirt1 activation or overexpression can inhibit pulmonary fibrosis in vitro via inactivation of TGF-β1/Smad3 and mTOR signaling." (PMID 34925016, 2021). "SIRT1 expression is significantly elevated in fibrotic areas of lungs from patients with idiopathic pulmonary fibrosis (IPF) and in the experimental model of bleomycin (BLM)-induced lung fibrosis." (PMID 32630813, 2020). "For example, inhibition of the miR-34a-mediated SIRT1/mTOR signaling pathway attenuates D-gal-induced senescence in rat brain tissue, and alveolar epithelial cell dysfunction is alleviated in aged miR-34a−/− pulmonary fibrosis mice." (PMID 40110129, 2025). "For instance cigarette smoking downregulates SIRT1, leading to dysregulation of lipid metabolism and activation of lung fibroblasts, thereby promoting the development of idiopathic pulmonary fibrosis, SIRT1 activator SRT1720 counteracted the effect of CS on NOX4, SOD2, PPARα and CPT1a in vivo." (PMID 39335456, 2024). "Thus, the Sirt1/Pgc-1α pathway exerts its antifibrotic effect on lung fibrosis by mediating the antioxidative and antisenescent effects of senegenin." (PMID 38929114, 2024). "Implying that targeting myofibroblast differentiation via the SIRT1/Nrf2 signaling pathway may constitute a pivotal strategy for liquiritigenin-based therapy against pulmonary fibrosis." (PMID 38238857, 2024). "Our findings imply that targeting myofibroblast differentiation via the SIRT1/Nrf2 signaling pathway may constitute a pivotal strategy for liquiritigenin-based therapy against pulmonary fibrosis." (PMID 38238857, 2024). "In addition to Sirt3, other members of the sirtuin family, such as Sirt1 and Sirt6, have demonstrated anti-pulmonary fibrosis effects through the inhibition of cellular senescence." (PMID 39062010, 2024). "The researchers further showed that a drug that tips the balance in favor of SIRT1 stabilization could prevent early senescence in an animal model of pulmonary fibrosis, a currently incurable lung disorder." (PMID 37258580, 2023). "However, neither knockout nor overexpression of Sirt1 influenced the severity of the lung fibrosis phenotype, suggesting that SIRT1 in AT2-lineage cells is dispensable in the pathogenesis of BLM-induced lung fibrosis." (PMID 37653024, 2023). "In addition, SIRT1 activation or overexpression can also attenuate pulmonary fibrosis via regulation of TGF-β1/p300 signalling." (PMID 37483618, 2023). "SIRT1 has possible implications for bleomycin-induced lung fibrosis." (PMID 36457607, 2022). "Patients with systemic sclerosis-associated lung fibrosis have decreased SIRT1 mRNA in PBMCs compared to those without lung involvement." (PMID 36457607, 2022). "Besides SIRT1 and SIRT3, SIRT7 has additionally been recently proposed as a novel regulator of lung fibrosis, and directly implicated in SSc-ILD." (PMID 35268452, 2022). "In addition to pulmonary fibrosis, SIRT1 and SIRT3 deregulation appears to also contribute to skin fibrosis." (PMID 35268452, 2022). "Among these Sirtuins, Sirt1, Sirt3, Sirt6, and Sirt7 have been well studied in pulmonary fibrosis." (PMID 34925016, 2021). "Furthermore, bleomycin reduced the expression levels of SIRT1 in the BALF of mice with pulmonary fibrosis; the reduced levels of SIRT1 subsequently elevated the levels of NF-κBp65 and promoted lung inflammation." (PMID 33693011, 2021). "In mice, this pathway inhibits Sirt1 silencing mediated by miR-34a and promotes the stability of Sirt1 mRNA during myogenic differentiation; furthermore, it attenuates pulmonary fibrosis, enhancing the stability of Sirt1 and increasing its expression during the epithelial-mesenchymal transition." (PMID 34575829, 2021).
pulmonary fibrosis (continued). "Interestingly, induction of SIRT-1 by resveratrol has been shown to ameliorate bleomycin-induced pulmonary fibrosis by inhibiting the recruitment of inflammatory cells, reducing epithelial-mesenchymal transition and TGF-β-mediated extracellular matrix production." (PMID 38678247, 2024). "Thus, it is necessary to determine whether SIRT1, Cdh1, and AROS are functionally associated with pulmonary fibrosis." (PMID 37258580, 2023). "Therefore, activating SIRT1 may be a valuable treatment against pulmonary fibrosis or CS-related disorders." (PMID 35568871, 2022). "In particular, circulating SIRT1 and SIRT3 were found to be decreased in patients with dcSSc in respect to patients with lcSSc, and showed an association with the extent of skin involvement (i.e., mRSS), the presence of lung fibrosis on HRCT scan of the chest, and worse pulmonary function." (PMID 35268452, 2022). "Therefore, targetted improvement of sirt-1 production in obese patients with pulmonary fibrosis may be a novel therapeutic strategy." (PMID 35115954, 2021). "Thus, the current study may shed light on SIRT1 influence in the evolution of lung fibrosis with age." (PMID 32630813, 2020). "Exogenous zinc supplementation and activation of SIRT1 promote the self-renewal and differentiation of AT2 cells in the lungs of IPF patients and aged mice, thereby reducing pulmonary fibrosis." (PMID 40241794, 2025). "It has been confirmed that SIRT1, SIRT2, SIRT3, SIRT6 and SIRT7 significantly inhibit the development of lung fibrosis." (PMID 40241794, 2025). "SIRT1, a crucial NAD + -dependent deacetylase, plays a pivotal role in combating or delaying pulmonary fibrosis while also serving as a key antioxidant." (PMID 38238857, 2024). "Overall, our study provides the first evidence of the reciprocal regulation of SIRT1 stability by APC/C-Cdh1 and AROS during stress-induced premature senescence, and our findings suggest pinosylvin as a potential senolytic agent for pulmonary fibrosis." (PMID 37258580, 2023). "Our results are in line with previous studies reporting that both SIRT1 and SIRT3 are important regulators of lung fibrosis, as they are able to attenuate TGFβ-mediated profibrotic responses both in vitro and in vivo." (PMID 35268452, 2022). "Several researchers have reported that SIRT1, SIRT3, SIRT6, and SIRT7 significantly deter the development and progression of lung fibrosis of different etiologies." (PMID 36457607, 2022). "Resveratrol, an activator of SIRT1, inhibits BLM-induced lung fibrosis in mice through the reduction of EMT." (PMID 36457607, 2022). "SiRT-1/AKT/mTOR pathway is implied in numerous fibrotic conditions, as liver, cardiac, kidney, and pulmonary fibrosis." (PMID 36301384, 2022). "Activation of SIRT1 increases ACE2 expression, and pharmacological activation of SIRT1 has been shown to attenuate ARDS and lung fibrosis." (PMID 39086962, 2022). "AE improved HFD-induced pulmonary fibrosis by suppressing IL-17, TGF-β, NE, and MMP-9 expression and activating IL-10 and sirt-1 expression." (PMID 35115954, 2021). "The relationship between SIRT1 and TGF-β has often been studied in idiopathic pulmonary fibrosis (IPF)." (PMID 32823491, 2020). "Tenuigenin also inhibited epithelial cell oxidation and senescence through the Sirtuin 1/peroxisome proliferators-activated receptor γ (PPAR-γ) coactivator 1 alpha pathway, alleviating pulmonary fibrosis, and protected against Staphylococcus aureus-induced pneumonia in mice." (PMID 41024189, 2025). "Furthermore, studies have indicated that SIRT-1 acts as a target for anti-pulmonary fibrosis drugs and inhibits the EMT in BLM-induced pulmonary fibrosis in mice." (PMID 38001499, 2023). "To clarify whether acetylation of C/EBPβ is necessary for pulmonary fibrosis, we subsequently investigated the effect of deacetylation of C/EBPβ on EMT using SIRT1." (PMID 33663392, 2021).